MAGEL2 (MAGE family member L2)
Diseases named in the same sentence as MAGEL2 in open-access papers (continued):
Sharing a sentence is not in itself a finding about the gene and the disease.
Anxiety (5 papers, 2016 to 2025). Intense feelings of nervousness, tension, or panic often arise in response to interpersonal stresses. "Our results suggest that the Magel2 gene in ARCPomc neurons, especially in males, influences the impact of stress on anxiety-like behavior and spatial learning deficits associated with a food reward." (PMID 41321745, 2025). "The Magel2 and Snord116 knockouts had increased anxiety, and the Ndn-deficient mice showed improved spatial learning and memory as well as skin-scraping—a behavior commonly observed in PWS patients." (PMID 27857842, 2016). "We sought to determine whether knockdown of Magel2 expression in ARCPomc neurons that innervate the MeA causes an increase in anxiety-like behavior." (PMID 41321745, 2025). "Our findings suggest that the loss of the Magel2 gene may influence the impact of stress on anxiety-like behavior in male mice." (PMID 41321745, 2025). "Hence, our current findings, along with previous ones, support the idea that the loss of function of the Magel2 gene may contribute to an enhanced impact of stress on anxiety-like behavior." (PMID 41321745, 2025). "We then explored the impact of Magel2 gene deletion in MeA-innervating ARCPomc neurons on anxiety-like behavior as anxiety is very common in individuals with PWS." (PMID 41321745, 2025). "Anxiety, interactions with novel objects or social interactions are altered in Necdin-KO and Magel2-KO mice, with a variability in the severity of the phenotype, partly due to the environmental context." (PMID 40048253, 2025). "In the Pavlovian fear-conditioning test, Magel2 ko mice exhibited significantly higher absolute freezing rates following the tone compared to wild-type controls, suggesting increased anxiety." (PMID 41321745, 2025). "In this study, we specifically deleted the Magel2 gene in ARCPomc neurons that innervate the MeA, given that the MeA is a critical structure involved in emotional behaviors, particularly anxiety-like behavior." (PMID 41321745, 2025). "In evaluations of behavioral features across several domains, juvenile Magel2 mutant rats displayed alterations in anxiety-like behavior and sociability measures." (PMID 36637363, 2023). "However, male mice with a Magel2 gene deletion in these particular neurons exhibit increased stress-induced anxiety-like behavior and reduce motivation/spatial learning, while female mice do not show these behavioral changes." (PMID 41321745, 2025). "We thus examined if acute stress such as restraint affects anxiety-like behavior in male mice lacking the Magel2 gene in MeA-innervating ARCPomc neurons." (PMID 41321745, 2025). "Given that anxiety is a prominent phenotypic behavior in PWS, it is plausible that the Magel2 gene in ARCPomc neurons, which project to the MeA, might be involved in the onset of anxiety rather than regulating feeding behavior in individuals with PWS." (PMID 41321745, 2025). "Both male and female mice lacking the Magel2 gene in MeA-innervating ARCPomc neurons display no alterations in anxiety-like behavior during the open field test, light/dark test, and elevated plus maze test in the absence of exposure to acute stress." (PMID 41321745, 2025). "In this study, we found that deleting the Magel2 gene in MeA-innervating ARCPomc neurons did not affect anxiety-like behavior in both male and female mice in the absence of acute stress exposure, aligning with prior findings." (PMID 41321745, 2025). "Interestingly, although anxiety is the most prevalent behavioral change in Prader–Willi syndrome (PWS), Magel2 ko mice did not exhibit anxiety-related behavior in the open field maze and elevated plus maze assessments in both male and female mice." (PMID 41321745, 2025).
arthrogryposis (4 papers, 2016 to 2026). A rare, non-progressive congenital disorder characterized by multiple joint contractures which are present at birth. "One additional, unrelated individual with a de novo truncating pathogenic variant in MAGEL2 was identified by Sanger sequencing of MAGEL2 in a cohort of individuals with arthrogryposis and/or decreased fetal mobility." (PMID 28933382, 2016). "Mutations in MAGEL2 and L1CAM have been associated with congenital hypopituitarism and arthrogryposis in a small series, highlighting the need for further study." (PMID 41499205, 2026). "It is known that human SYS patients have ASD and arthrogryposis, and Magel2-null mice have altered circadian rhythm, reduced motor activity, and increased adiposity." (PMID 32804975, 2020).
hypogonadism (3 papers, 2014 to 2025). A disorder characterized by decreased function of the gonads. "PWS is also characterized by endocrinopathies including growth deficiency, hypogonadism, and delayed puberty onset, which we also observed in our Del Ndn-Magel2 mouse model." (PMID 40048253, 2025). "The loss of Magel2 in mice leads to the reduction in male and female fertility by extending breeding intervals and early reproductive decline and termination, which is consistent with the symptoms of hypogonadism in patients with SYS." (PMID 36836222, 2023).
Prader-Willi-like syndrome (3 papers, 2024 to 2025). "For example, MAGEL2 deletion has been associated with Prader-Willi-like syndrome (ORPHA ID:398,069), including a UPD case (ORPHA ID:98,754) with a role for the SNRPN, OCA2, MAGEL2, and NDN genes." (PMID 38902749, 2024).
central precocious puberty (2 papers, 2019 to 2021). "Additionally, we found 29 case reports that described abnormalities in only MAGEL2 (associated with Schaaf–Yang syndrome) and 42 case reports with abnormalities in only MKRN3 (associated with central precocious puberty), which are not included in the table." (PMID 34200226, 2021).
congenital heart disease (2 papers, 2020 to 2023). A heart disease that is present at birth. "MAGEL2 was described to be paternally expressed in heart of pigs, but the mechanism of the MAGEL2 variants to the congenital heart disease, for example, whether MAGEL2 variants perturb the normal program of cardiac development, remains unclear." (PMID 32702813, 2020). "Relevant to SYS, fatal cases of congenital heart disease have been reported in MAGEL2 patients, making these cardiac findings especially relevant." (PMID 36637363, 2023). "Worthy of note is the phenotype of congenital heart disease present in our patients but not described in other patients with MAGEL2 variants." (PMID 32702813, 2020).
Failure to thrive (2 papers, 2009 to 2022). Failure to thrive (FTT) refers to a child whose physical growth is substantially below the norm. "We have previously reported an early failure to thrive in Magel2-null neonates followed by adult-onset weight gain and increased adiposity, but this weight difference is no longer apparent at the normal timing of puberty." (PMID 19172181, 2009).
Hypoglycemia (2 papers, 2023 to 2025). A decreased concentration of glucose in the blood. "Female Magel2-null mice failed to respond to hypoglycemia with increased corticosterone, suggesting MAGEL2 deficiency might contribute to adrenal insufficiency." (PMID 37685915, 2023). "Magel2-null mice had elevated basal corticosterone levels, and although male Magel2-null mice had an intact corticosterone response to restraint and to insulin-induced hypoglycemia, female Magel2-null mice failed to respond to hypoglycemia with increased corticosterone." (PMID 41516228, 2025).
Infertility (2 papers, 2009 to 2013). "We now show that loss of Magel2 affects both male and female reproduction, causing reduced fertility and early infertility in both males and females, delayed puberty and irregular estrus cycles in females, and low testosterone, and impaired olfaction and olfactory preference in males." (PMID 19172181, 2009). "The reduced fertility of Magel2-null mice is consistent with that seen in other circadian mutant mice, but subtler than the infertility and incomplete sexual maturation seen in PWS." (PMID 19172181, 2009). "We previously showed that gene-targeted mice lacking Magel2 become overweight with increased adiposity as adults, and exhibit delayed puberty, irregular estrous cycles, and early onset infertility." (PMID 23341784, 2013).
Apnea (1 paper, 2024). Lack of breathing with no movement of the respiratory muscles and no exchange of air in the lungs. "Deletion outcomes vary by type (ORPHA ID: 98,793, ORPHA ID: 177,901), including type 2 genes such as SNORD116-1, SNRPN, SNORD115-1, OCA2, MAGEL2, NDN, and their role in the development of apnea." (PMID 38902749, 2024).
C syndrome (1 paper, 2017). C syndrome is a rare multiple congenital anomaly/intellectual disability syndrome characterized by trigonocephaly and metopic suture synostosis, dysmorphic facial features, short neck, skeletal anomalies, and variable intellectual disability. "Given the uncertain role of CD96 in OTCS MAGEL2 might be the first gene clearly associated with Opitz C syndrome." (PMID 28281571, 2017).
depression (1 paper, 2016). "The decreased expressions of mRNAs in CUMS-induced depression mice include Slc6a11, Hap1, Gad1, Gad2, Gng4, Slc32a1, Doc2g, Slc32a1, Magel2, Prkcd, Ngfr, Dusp1, Th, Itih3, Cacna2d2, Arc, Mbp, Peg10, Fos, and so on." (PMID 27427907, 2016).
Down syndrome (1 paper, 2023). "Social processes in individuals with MAGEL2-related disorders are disrupted, as ASD and social deficits are frequently reported; reduced sociability has also been reported in individuals with PWS compared to individuals with Down syndrome." (PMID 36637363, 2023).
glioblastoma (1 paper, 2024). The most malignant astrocytic tumor (WHO grade IV). "MAGEL2, where 37% NB tumours displayed LOM and 28% Intermediate LOM, belongs to a highly conserved group of proteins (MAGE-The Melanoma Antigen Gene), which are reported to be deregulated in multiple cancers including central nervous system tumours medulloblastoma and glioblastoma." (PMID 39217334, 2024).
glioma (1 paper, 2020). A benign or malignant brain and spinal cord tumor that arises from glial cells (astrocytes, oligodendrocytes, ependymal cells). "This analysis revealed that some MAGEs including MAGED subfamily are overexpressed, while most others including MAGEE1, MAGEE2, MAGEL2, MAGEH1, NDN, and TRO are downregulated in glioma." (PMID 33425727, 2020). "Further, other downregulated T2Ms in glioma, including MAGEE1, MAGEL2, TRO, and NDN also exhibited similar negative correlations with immune cell infiltration in LGG, while in GBM they showed a varying degree of positive correlations with infiltration of different immune cells." (PMID 33425727, 2020).
Hao-Fountain syndrome (1 paper, 2026). "Furthermore, we determine the high-resolution crystal structure of the TRAF/MAGEL2 complex and identify Hao-Fountain syndrome-linked mutations in USP7 that disrupt USP7/MAGEL2 complex formation in vitro and in cells." (PMID 42094436, 2026).
obstructive sleep apnea (1 paper, 2023). "Third, the finding that Magel2 mutant rats experience altered apnea metrics compared to wild-type littermates is interesting when considering elevated rates of obstructive sleep apnea in SYS." (PMID 36637363, 2023).
sleep-disordered breathing (1 paper, 2025). "Combined deletion of Magel2 and Necdin (NdN-Magel2 double knockouts) results in a more pronounced phenotype, including exacerbated sleep-disordered breathing and apneic episodes." (PMID 41516228, 2025).
spinal muscular atrophy (1 paper, 2024). A motor neuron disease that affect the muscles, and characterized by muscle weakness and atrophy resulting from progressive degeneration and irreversible loss of the anterior horn cells in the spinal cord (i.e., lower motor neurons) and the brain stem nuclei. "We correlate mutations within MAGEL2 to spinal muscular atrophy and autism and also demonstrate its influence on the abundance of SNORD116." (PMID 38908375, 2024).
neurodevelopmental disorder (9 papers, 2018 to 2025). A behavioral and cognitive disorder with onset during the developmental period that involves impaired or aberrant development of intellectual, motor, or social functions. "The MAGEL2 gene is in the microdeletion region associated with Prader–Willi syndrome (PWS), a neurodevelopmental disorder phenotypically similar to SYS." (PMID 34265304, 2021).
cancer (6 papers, 2015 to 2025). A tumor composed of atypical neoplastic, often pleomorphic cells that invade other tissues. "Because MAGEL2 cellular functions have previously been investigated only in cancer cell models, we first examined the role of MAGEL2 in endosome-mediated protein trafficking in DPSC-derived neurons to validate this PWS model system." (PMID 32879135, 2020). "The physiological role of MAGEL2 is best described using cancer cell models, where MAGEL2 partners with E3 ubiquitin ligases to facilitate protein trafficking through the retromer pathway." (PMID 32879135, 2020). "Type I MAGEs are all reported to be cancer-testis antigens, and located on the X-chromosome, whereas Type II MAGEs are ubiquitous in expression and some members such as MAGEL2 are located on autosomes." (PMID 32760472, 2020). "Many of these genes have previously been reported in cancer and also in the context of NB including NNAT, RB1, MAGEL2, GPR1, NDN." (PMID 39217334, 2024). "MAGEL2, a Type II MAGE, on the other hand, is ubiquitously expressed in non-transformed and cancer cells." (PMID 40141091, 2025).
tumor (6 papers, 2019 to 2024). "In support of a role for Magel2 in endocytic recycling, a study using Magel2-deficient mice and tumor cell line models revealed that cell surface recycling of the leptin receptor is impaired." (PMID 32879135, 2020). "MAGEL2 belongs to the MAGE family proteins that were initially identified as tumor-specific antigens." (PMID 31791363, 2019).
neurological disease (3 papers, 2014 to 2024). "The abnormality of Magel2 has been confirmed to be involved in neurological disease development." (PMID 38589422, 2024). "The regions of the 3 CNVs are located in chromosome Xp22.31, 15q11.2–13.1 and 17p11.2, and harbored genes associated with neurological diseases including GABRB3, UBE3A, MAGEL2, RAI1, ALDH3A2, ATPAF2 according to the database of Online Mendelian Inheritance in Man (OMIM)." (PMID 33753861, 2021).
metabolic disorder (1 paper, 2025). "A study investigating a metabolic disorder characterized by MAGE Family Member L2 (MAGEL2) deficiency revealed that this deficiency is related to neuroinflammation in the brain." (PMID 39800721, 2025).
MAGEL2 also shares sentences with these, for which no sentence is quoted: genetic disorder (3 papers); arthrogryposis multiplex congenita (2); mental disorder (2); Adrenal insufficiency (1); central precocious puberty 2 (1); congenital hypopituitarism (1); congenital myasthenic syndrome (1); cryptorchidism (1); Dyskinesia (1); endocrinopathies (1); epilepsy (1); glutaric acidemia (1); growth deficiency (1); Hepatic steatosis (1); infection (1); insomnia (1); Insulin resistance (1); male infertility (1); medulloblastoma (1); mitochondrial complex I deficiency (1); motor neuron diseases (1); trigonocephaly (1).